MEG3 (maternally expressed 3)
Diseases named in the same sentence as MEG3 in open-access papers (continued):
Sharing a sentence is not in itself a finding about the gene and the disease.
diabetes (40 papers, 2016 to 2025). "Taken together, our results revealed an association of MEG3 gene polymorphisms with the risk of developing neuropathy in patients with diabetes." (PMID 40765563, 2025). "Encoded in the DLK1-MEG3 locus on Chromosome 14q32, maternally expressed gene 3 (MEG3) has been extensively studied in cancer, diabetes, renal ischemia, and CVDs." (PMID 39049097, 2024). "For instance, MEG3 expression is strongly associated with diabetes, and its expression is downregulated in pancreatic islets of type 1 (T1D) and type 2 diabetes (T2D) in mouse and human." (PMID 37670346, 2023). "The imprinted genes Gtl2/Meg3 have also been implicated in transgenerational diabetes risk in the mouse model." (PMID 38288471, 2023). "MEG3 SNPs are associated with multiple diseases including asthma, inflammatory response, diabetes, stroke, and cancer." (PMID 36726728, 2023). "A literature survey also found MEG3 consistently linked to IR injury and obesity/diabetes, validating it, or molecules in its pathway, as a therapeutic target in IGCA." (PMID 36147743, 2022). "The loss of genomic imprinting (LOI) expression of DLK1-Dio3 miRNAs in acute promyelocytic leukemia (APL) and type 2 diabetes mellitus (T2DM) has been associated with altered DNA methylation at Gtl2 (MEG3)-DMR region." (PMID 27070142, 2016). "Notably, two of them, Meg3 and Tmed10, have been linked to exocrine pancreatic differentiation in prior studies, especially in the context of diabetes mellitus." (PMID 41331466, 2025). "In addition to conferring the susceptibility to various types of cancer 32-34, MEG3 rs7158663 was recently shown to be associated with renal 35 and ocular complications 36 of diabetes." (PMID 40765563, 2025). "Thus, the aim of this study was to investigate the potential association between the MEG3 rs7158663 SNP and susceptibility to DR in patients with type 2 diabetes mellitus (T2DM) from a Brazilian population." (PMID 39529988, 2024). "Furthermore, a study of patients with diabetes revealed an association between a SNP (rs941576), located on an intron of MEG3, with T1DM." (PMID 30469430, 2018). "In addition, we demonstrated that fucoidan alleviates myofibroblast activities by targeting the MEG3/miR-181a/Egr1 axis, and this MEG3 network might depend on the type of tissues or pathogenic mechanism (areca nut chewing, diabetes, and inflammation)." (PMID 35890132, 2022). "Firstly, there are numerous complications associated with diabetes (e.g. ocular, renal, cutaneous, and cardiovascular conditions), and the genetic architecture of each comorbidity could potentially influence our result regarding the association of MEG3 gene variations with DN." (PMID 40765563, 2025). "For the differentially expressed lncRNAs identified, MIR7-3HG, LINC01116, HIF1A, MEG3, XIST, NEAT1, and HHLA3 have been previously associated with some form of diabetes and diabetes-associated complications." (PMID 38326874, 2024). "LncRNAs such as lncRNA-ZFAS1, lncRNA Meg3, miR-182-5p and miR-378a-3p have been shown to affect the occurrence and development of diabetes and its complications by regulating the ferroptosis pathway." (PMID 36225311, 2022). "Given the relevant role of the body-mass index (BMI), obesity and diabetes as comorbidities in iGCA, we also performed a literature search in order to determine MEG3 direction of expression in these circumstances." (PMID 36147743, 2022). "Predecessors in the study of diabetes found that the promoter region of MEG3 can undergo DNA methylation and that DNA methylation can reduce the expression of target genes." (PMID 31584879, 2019). "In the ceRNA network, mmu-miR-93-5p were potential target microRNA of Meg3, and played a vital role in inflammation, cancer, Alzheimer’s disease, and diabetes." (PMID 31761787, 2019).
diabetes (continued). "Recently, it has been shown that microRNAs in the DLK1-MEG3 gene cluster are dramatically downregulated due to increased methylation at the MEG3-DMR in pancreatic islets of Type 2 diabetes mellitus patients." (PMID 31246962, 2019). "For example, down-regulation of MEG3, a microRNA gene, by parent-specific methylation has been observed in pancreatic islets of Type 2 diabetes mellitus patients, thus providing mechanistic support for co-localisation of non-coding RNA and ASM." (PMID 31594537, 2019). "In addition to tumorigenesis, fluctuations in MEG3 expression levels have been correlated with the development of many diabetes-related complications." (PMID 40765563, 2025). "MEG3 is downregulated in the islets and blood of individuals with diabetes, and in a murine β-cell line (MIN6), MEG3 seems to regulate insulin synthesis and secretion since its absence reduced the expression of key factors for β-cell function (PDX-1 and MAFA), decreasing insulin synthesis." (PMID 38326874, 2024). "Several SNPs in MEG3 have been reported in literature that may affect MEG3 expression and influence the risks of various diseases including inflammatory response, diabetes, stroke, and cancer." (PMID 36726728, 2023). "Moreover, analysis of 53 peripheral blood samples from individuals with type 2 diabetes mellitus (T2DM) showed that MEG3 is related to the progression of T2DM and can be used as a novel biomarker for clinical diagnosis." (PMID 36968595, 2023). "Moreover, in response to Meg3-siRNA, the effects of ferritin lysis were reversed, which exacerbated the occurrence of ferroptosis and affected the development of diabetes and its complications." (PMID 36225311, 2022). "This study showed that high glucose could affect the expression of lncRNA MEG3 and govern the miR-483-3p/ERp29 proteins in HCC patients, suggesting that management of lncRNA MEG3 could be promising for the treatment of HCC patients with diabetes." (PMID 36313695, 2022). "Given that maternally expressed MEG3 is a long-noncoding RNA playing a role in angiogenesis and diabetes-related microvascular dysfunction, altered MEG3 methylation under the prenatal condition may relate to adult health such as CVD." (PMID 32903514, 2020). "Studies on MEG3 in patients with diabetes have shown that DNA methylation may occur in the promoter region, resulting in decreased expression of MEG3 and affecting the occurrence and development of the disease." (PMID 31584879, 2019). "Additionally, Meg3 was shown to promote insulin resistance in a mouse model of type 1 diabetes mellitus (T1DM) and T2DM." (PMID 30469430, 2018). "Furthermore, MEG3 has been reported to be increased in plasma samples from patients with diabetes." (PMID 39049097, 2024). "Thus, MEG3 upregulation may serve as a new therapeutic approach in the treatment of diabetes-induced microvascular complications." (PMID 30669611, 2019). "Thus, up-regulation of MEG3 may serve as a therapeutic strategy for treating diabetes-related microvascular complications." (PMID 29074557, 2017). "In conclusion, our study revealed the upregulation of the lncRNAs MALAT1,MEG3, and TUG1 in patients within the first five yearsof diagnosis of T1DM compared to controls and long-term diabetes group." (PMID 41123190, 2025). "Our EWAS identified DNAm candidates known to be modified by diabetes relevant environmental factors including diet and glucose levels (CLIP2, GNAS/GNAS-AS, MEG3)." (PMID 38915393, 2024). "Only in this case can we better understand the exact functions of Meg3 and its five downstream genes in human BAT and also uncover mechanisms related to the development and progression of obesity and diabetes." (PMID 32614631, 2020). "Multivariate logistic regression analysis initially included the following variables: age, gender, hypertension, diabetes mellitus, TCH, TG, HDL-C, LDL-C, MEG3 rs7158663, rs4081134 and miR-181b rs322931." (PMID 30579356, 2018).
diabetes (continued). "In the context of diabetes, MEG3 expression has been described as being notably downregulated in islets from patients with T2DM compared with those from controls without diabetes." (PMID 39529988, 2024). "In a diabetic environment, retinal epithelial cells expressed lower levels of MEG3 and SIRT1 and higher levels of miR-34a, meaning that diabetes could inhibit MEG3 and SIRT1 expression and increase miR-34a expression." (PMID 37762249, 2023). "However, although CIRI patients with diabetes have a worse prognosis, the involvement of lnc‐MEG3 in its pathophysiology has not been reported." (PMID 39912333, 2025). "Although several lncRNAs, including HILNC25, lncRNA MEG3, and MALAT-1, have been found to contribute to diabetes, little is known about the expression profiles of lncRNAs in T1DM patients and whether lncRNAs can be used as diagnostic or prognostic tool for T1DM." (PMID 32719778, 2020).
meningioma (37 papers, 2013 to 2025). A generally slow growing tumor attached to the dura mater. "It has been reported that loss of MEG3 was correlated with tumor grade; in meningiomas, MEG3 has been detected in four of nine grade I, one of eleven grade II, and none of seven grade III." (PMID 36851033, 2023). "Similar to the MEG3 gene, biallelic loss and promoter methylation has been observed in high-grade meningiomas, but only allelic loss correlated with gene silencing." (PMID 33014773, 2020). "Allelic losses, promoter hypermethylation and reduced expression of MEG3 gene have been associated to aggressive meningioma phenotype." (PMID 27429002, 2016). "The maternally expressed gene 3 (MEG3) located in the 14q32 region has been implicated in meningioma progression, too." (PMID 27429002, 2016). "In meningiomas, loss of MEG3 expression, its deletion at the genomic DNA and the degree of methylation of its promoter, have all been associated with higher tumor growth." (PMID 25965831, 2015). "In normal pituitary cells MEG3 is expressed, the loss of expression is observed in pituitary adenomas and the majority of meningiomas and meningioma cell lines." (PMID 23443164, 2013). "MEG3 allelic loss of locus is associated with meningioma pathogenesis and progression." (PMID 34512715, 2021). "Several studies reveal that the low expression of MEG3 in adenoma, meningioma, and neuroblastoma is directly related to the trimethylation of Lys‐27 in histone 3 (H3K27me3) of the MEG3 gene promoter." (PMID 36468944, 2023). "Higher expression of MEG3 works in a tumor suppressive manner by oppressing cell proliferation in meningioma and HCC cell lines." (PMID 36359888, 2022). "Recurrent hypermethylation in the MEG3 promoter is commonly seen in human tumors, such as pituitary cancer, meningioma, and leukemia." (PMID 36359888, 2022). "A previous investigation indicates MEG3 modulates cell proliferation by sponging miR-29 c in meningioma, pinpointing the regulatory relationship between MEG3 and miR-29 c again." (PMID 34558385, 2021). "On the other hand, MEG3 is a possible tumor suppressor lncRNA in meningioma, which modulates invasive properties of these cells through the miR-29c/AKAP12 axis." (PMID 34885097, 2021). "Meanwhile, SNHG1, LINC00702, LINC00460, and MEG3 have been found to partake in the pathogenesis of meningioma." (PMID 34885097, 2021). "Factually, it has been reported that lncRNA MEG3 expression level correlated with tumor grade and prognosis in meningiomas." (PMID 31938020, 2020). "Moreover, MEG3 was located on chromosome 14q32.3, a site that has been predicted to contain a tumor suppressor gene involved in the pathogenesis of meningiomas." (PMID 39346787, 2024). "In addition, changes in DNA methylation levels or expression of specific genes (e.g., NRDG2, MEG3, PDGFR, etc.)are also closely associated with the development of meningiomas." (PMID 36969005, 2023). "Hypermethylation in the MEG3 promoter was also found in meningiomas and neuroblastoma cell lines." (PMID 36851033, 2023). "In summary, this finding implies that MEG3 is a tumor suppressor in meningioma." (PMID 36544907, 2022). "The increase of VEGF pathway activity in MEG3 KO mice brain suggests that MEG3 may play an important role in the progression for tumors like meningioma." (PMID 29069869, 2017). "It has been reported that MEG3 has anti-proliferative and anti-tumour activity in meningiomas." (PMID 27429002, 2016).
meningioma (continued). "Altogether, these findings suggest that MEG3 may have an important role as a novel long non-coding RNA tumor suppressor in meningiomas." (PMID 25965831, 2015). "Promoter methylation of MEG3, GSTP1, and MAL2 has been shown to more commonly in higher grade meningiomas." (PMID 33194703, 2020). "Studies have revealed that MEG3 is expressed in many normal tissues, but not in the majority of human meningiomas or human meningioma cell lines." (PMID 24036441, 2013). "Recently, a team from Fujian Medical University found that MEG3 mediated meningioma cell cycle arrest through miR-29c/A-kinase anchoring protein 12 (AKAP12) axis and inhibited tumor cell migration, invasion, and proliferation; thus, providing a new biomarker for the treatment of meningioma." (PMID 36544907, 2022). "MEG3 is not expressed in the majority of human meningiomas or the human meningioma cell lines." (PMID 24069260, 2013).
prostate carcinoma (33 papers, 2011 to 2025). A carcinoma that arises from epithelial cells of the prostate gland. "This study aimed to investigate the association between the anti-prostate cancer (PCa) effect of niraparib, a representative PARPi, and MEG3 expression, as well as explore the downstream pathway involved." (PMID 38047026, 2023). "Another preclinical study demonstrated that upregulation of MEG3 in prostate cancer (PCa) cell lines induced apoptosis and G0/G1 phase arrest, to inhibit the expression of Bcl-2 and Cyclin D1." (PMID 40242248, 2025). "This regulatory role on androgen signals offers a distinct but synergistic mechanism alongside MEG3’s modulation of epigenetic and miRNA pathways, enhancing the overall suppression of tumor growth and metastasis in prostate cancer." (PMID 40242248, 2025). "Overall, these results highlight the therapeutic potential of MEG3, opening up opportunities for its clinical application in prostate cancer treatment." (PMID 40242248, 2025). "Among them, MEG3 was found to be down-regulated in prostate cancer and modulated the miR-9-5p/QKI-5 axis; thus, affecting cell proliferation, migration, invasion, and apoptosis rate." (PMID 40242248, 2025). "Collectively, these studies demonstrate the diverse regulatory functions of MEG3 in prostate cancer, providing potential insights into its impact on cancer progression and facilitating the identification of novel therapeutic targets for this disease." (PMID 40242248, 2025). "LncRNA MEG3 was reported to affect proliferation and migration of prostate cancer cells through regulating miR-9-5p/QKI-5 axis." (PMID 38824534, 2024). "MEG3 has been implicated in upregulating the expression of BAX and caspase 3, as demonstrated in prostate cancer." (PMID 39108882, 2024). "For example, the expression of MAGI2-AS3 and MEG3 in lncRNAs inhibits the development of prostate cancer, and MNX1-AS1 indirectly promotes the development of prostate cancer through expression." (PMID 38233788, 2024). "Niraparib restrains prostate cancer cell proliferation and metastasis and tumor growth in mice by regulating the lncRNA MEG3/miR-181-5p/GATA6 pathway." (PMID 38047026, 2023). "For example, lncRNA MEG3 is less expressed in prostate cancer, which affects cell proliferation, migration, invasion ability and apoptosis rate by regulating miR-9-5p and QKI-5." (PMID 35109842, 2022). "LncRNA MEG3 has a downregulated in prostate cancer and impact on the abilities of cell proliferation, migration and invasion, and cell apoptosis rate." (PMID 34983363, 2022). "By targeting Bcl-2 in prostate cancer cells, Yao Shi discovered that MEG3 played a critical role in controlling cell proliferation, apoptosis, and migration." (PMID 34421993, 2021). "The results of qRT‐PCR revealed that the level of lncRNA MEG3 was significantly decreased in prostate cancer tissues." (PMID 30565858, 2019). "LncRNA MEG3 was a down‐regulated lncRNA in prostate cancer and impacted the abilities of cell proliferation, migration and invasion, and cell apoptosis rate, this regulation relied on regulating miR‐9‐5p and its targeting gene QKI‐5." (PMID 30565858, 2019). "Meanwhile, a lower level MEG3 was obtained in the 4 prostate cancer cell lines (PC‐3, DU145, VCaP and 22RV1) compared with the human prostate epithelial cell line WPMY‐1." (PMID 30565858, 2019). "Reduced MEG3 expression has also been observed in breast, cervical, colon, liver, lung, and prostate cancer cell lines." (PMID 28407691, 2017). "Similar changes in MEG3 levels have also been found in various brain, bladder, bone marrow, breast, cervix, colon, liver, lung, meninges, and prostate cancers-derived cell lines." (PMID 29069869, 2017). "For example, while MEG3 is highly expressed in normal brain tissues, this lncRNA was strongly decreased in our brain cancer datasets, and strikingly so in gall bladder, retinal and prostate cancers, consistent with the proposed tumor suppressor role for MEG3." (PMID 21991387, 2011).